CD4 (CD4 molecule)
Diseases named in the same sentence as CD4 in open-access papers (continued):
Sharing a sentence is not in itself a finding about the gene and the disease.
tumor (continued). "The tumor-infiltrating B cells (TIBs) play a multifaceted dual role in regulating tumor immunity rather than just tumor inhibition or promotion and affect the function of other immune cells such as CD4+ T cells and natural killer cells in the tumor microenvironment." (PMID 35359451, 2022). "Interestingly, in vivo depletion of CD4+ T cells potentiated the combination of low-dose Anlotinib and anti-PD-1 therapy, leading to tumor regression." (PMID 35990640, 2022). "Activated tumor-infiltrating Tregs (CD4+Foxp3+ICOS+Ki67-; cluster 13) were also significantly reduced in both combination chemo‐immunotherapy treated groups (5-FU+ICB: 0.25 ± 0.20%; cisplatin+ICB: 0.29 ± 0.31%) compared to PBS controls (2.73 ± 1.01%; p = 0.015; p = 0.014 respectively)." (PMID 35634282, 2022). "The experimental results of an in situ tumor-bearing mouse model showed that after PD-1 inhibitor therapy combined with radiotherapy, the ratio of CD4+/CD8+ T cells, neutrophils, IFN-γ, TNF, and IL-5 in the lung tissue of the mouse model increased, and inflammatory reactions increased." (PMID 35799264, 2022). "However, depleting CD4+ T cells significantly reduced the number of NK cells in the TME in that model, indicating that CD4+ T cells actively recruit NK cells to the tumor site." (PMID 35768424, 2022). "CD4+ VISTA+ T cells were significantly more infiltrated in tumor tissues." (PMID 35122478, 2022). "IFN‐γ could promote T cells differentiate to tumor‐specific CD4+ T cells and expansion of CTLs, while IL‐2 promoted activation and proliferation of NK cells." (PMID 35652198, 2022). "One study showed that CD69+ cells increased in the tumor cell area in CD4+ or CD8+ T cells." (PMID 36035394, 2022). "Interestingly, we observed a significant reduction in tumor-infiltrating CD4+ FoxP3+ T cells in 4NQO-exposed mice receiving BRB-E-supplemented feed compared to those receiving only the AIN-76 control diet." (PMID 36016924, 2022). "Expression of various combinations of inhibitory receptors by CD4+ TIL was also associated with A2AR antagonist treatment, as not further pursued here because of our focus on the direct interaction between CD8+ CTL and tumor target cells." (PMID 35013519, 2022). "Together, these results suggest that the anti-tumor effects of tumor-specific CD4+ T cells might have been underestimated." (PMID 35784297, 2022). "Previous study showed that PD-L1 inhibitor could induce expansion of tumor-infiltrating CD4+ and CD8+ T-cell subsets." (PMID 36612054, 2022). "A simplified system that modulates these functions could pave the way toward scalable, consistent CD4+ T cell or “helped” CD8+ T cell cancer therapies, while also providing mechanistic insight into CD4+ T cell tumor biology." (PMID 36241639, 2022). "Mechanistically, this was achieved through an enhancement in the expression of MHC class II proteins on intratumoral myeloid cells, increasing access by CD4+ tumor-infiltrating T cells, and decreasing the percentage of intratumoral T cells that express inhibitory immune checkpoint molecules." (PMID 36605208, 2022). "All these data suggested that the strong antitumor potential of cryo-thermal CD4+ T cells against tumor rechallenge could be attributed to CD4+ Th1-mediated antitumor immune memory." (PMID 35874660, 2022). "Such HLA-I deficiencies are thought to limit tumor antigen presentation to CD8+ T cells but do not account for the potential role of cytotoxic CD4+ T cells." (PMID 35831288, 2022). "Furthermore, TGFβ has been implicated in vivo to promote exclusion of CD4+ and CD8+ T cells within the tumor microenvironment." (PMID 36382087, 2022). "Also, positive correlations were found between frequencies of FoxP3+Helios− Tregs and CD4+PD-1+ T cells in PBMCs and TILs in advanced tumor stages, and a positive correlation in NILs only in early tumor stages." (PMID 36146549, 2022).
tumor (continued). "Interestingly, EBV-induced CD4+ T cells have the potential to exhibit cytotoxicity against EBV-negative tumors in vitro, suggesting a strategy to use EBV-specific CD4+ T cells for anti-tumor immunotherapy." (PMID 36077655, 2022). "Interestingly, while the ADC treatment increased the numbers of CD8 T cells in the tumors, it decreased the tumor CD4 T cell population." (PMID 36442099, 2022). "Treatment withintratumoral GLA-SE as an adjuvant to surgery and radiotherapy demonstrated safety and feasibility in Merkle cell carcinoma with increased intratumoral infiltration of CD8+ and CD4+ T cells, activation of immune-related genes, and local tumor regression." (PMID 36479129, 2022). "Both the percentage of TILs and the expression of different immune cells in the tumor microenvironment (CD8+, CD4+ Th1 and NK cells) have been associated with better prognosis; they may also contribute to the therapeutic effects of anti-HER2 targeted therapy." (PMID 35884366, 2022). "Activated tumor reactive CD4+ and CD8+ T cells can give rise to effector and memory cells." (PMID 35710296, 2022). "One objective in developing MHC II aAPCs was to produce a scalable approach for generating CD4+ T cells that could enhance the memory formation, function, and cytotoxicity of tumor-specific CD8+ T cells." (PMID 36241639, 2022). "Our data demonstrated that GPX8 was correlated with mRNA expression of immune markers of CD8+ T cells (CD8B), CD4+ T cells (CD4), T cells (CD3D), macrophages (CD68 and ARG1), neutrophils (ITGAM and CCR7), dendritic cells (NRP1), NK cells (B3GAT1), and tumor-associated fibroblasts (FAP)." (PMID 36061208, 2022). "Interestingly, ADI-PEG20 led to a marked increase in tumor-infiltrating CD4+ and CD8+ T cells in a syngeneic B16-F10-melanoma mouse model." (PMID 35898872, 2022). "In addition, main lymphocyte subsets involved in anti-tumor immunity, including CD4+ memory T cell, CD4+ Tcm, CD8+ T cell, DC, Macrophages, Mast cell, NKT cell, and Tregs were significantly increased in the low-risk subgroup." (PMID 36211401, 2022). "In our previous study, we found that CD4 T cells can reject tumors that do not express MHC class II molecules, suggesting that an MHC class II+ host cell may capture and present the tumor antigen to CD4 T cells at the tumor site." (PMID 35903540, 2022). "This may be explained not only by the potential pro-tumor activity of the regulatory frequency of CD4+ T cell but also by the antitumor of the frequency of CD8+ T cell." (PMID 35185898, 2022). "The cell cycle of tumor cells was also analyzed, and the result showed that CD4+ T cell derived IFN-γ could induce growth arrest in tumor cells." (PMID 35874660, 2022). "Tumor-derived DP CD4+ Th exhibit signs of activation and display a tumor-resident phenotype." (PMID 35439168, 2022). "We hypothesize that raised levels of circulating Hsp70 in higher tumor stages might support NK cell proliferation but that a lowered prevalence of CD4+ T helper cells tempers the capacity of cytolytic CD8+ T cells and NK cells to control tumor growth." (PMID 36428793, 2022). "For example, high infiltration of activated CD8+ and CD4+ T cells, such as in CMS1 tumors, is associated with good prognosis and less tumor recurrence, although multiple mechanisms of tumor immune evasion could still make these tumors resistant to therapies." (PMID 35269922, 2022). "CD4+ T cells, mainly T helper cells, broadly play an important adjuvant function in the recognition and clearance of tumor cells, through promoting the proliferation and activation of CTLs, the formation of memory CTLs, and enhancing the antigen presentation of DCs." (PMID 36532071, 2022). "Moreover, type 1 T helper (Th1) CD4+ and also CD8 + cells polarize innate immune cells versus tumor regression, for instance by M1 macrophages polarization of tumor-associated macrophages (TAMs)." (PMID 35392964, 2022).
tumor (continued). "In addition to influencing innate cells, CCL5 promotes tumor metastasis via the induction of CD4+ T cell polarization and enhances the infiltration and function of Tregs." (PMID 35327361, 2022). "Therefore, studying CD4+ Tconv contributes to our understanding of anti-tumor and the development of novel immunotherapeutic approaches." (PMID 35603183, 2022). "Remarkably, the application of vismodegib may even lead to an upregulation of MHC-I on BCC tumor cells and an increased infiltration of CD4+, CD8+, and HLA-DR-class II-positive cells like macrophages within the tumor cell nests." (PMID 35463364, 2022). "At least in this ex vivo model, the cytotoxicity kinetics suggest that CD4+ T cells may contribute to tumor cell killing over a longer period and potentially with higher specificity compared to conventional CD8+ CTLs." (PMID 36159781, 2022). "Furthermore, NCTD can positively regulate macrophage-mediated immune responses via the Akt/NF-κB pathway, and can decrease the number of tumor-infiltrating Tregs and increase the number of CD4 + and CD8 + T cells." (PMID 36463199, 2022). "However, it has been shown that antigen-mediated activation of both CD8 T cells and CD4 T cells is indispensable for a robust anti-tumor immune response." (PMID 36385142, 2022). "In addition, macrophages inhibit the anti-tumor effect of CD4 + T cells, and inhibit T cell proliferation by secreting several molecules like TGF-β and Arg-1." (PMID 35246045, 2022). "This strategy may increase the safety profile of the CD4 CAR-T cell product as it facilitates enhanced binding of the CAR-T cells to CD4+ tumor cells, thereby improving the chance of additional target engagement and killing of the tumor cells." (PMID 36059451, 2022). "After administration of a BRAFi in a BRAF-mutant melanoma model, CD40 ligand and interferon-gamma expression was increased on intratumoral CD4+ tumor-infiltrating lymphocytes (TIL), and regulatory T-cells and myeloid cells were decreased, suggesting anti-tumor modulation of the TME." (PMID 36505793, 2022). "As highlighted by previous papers, CD4+ T cells can play an important role in anti-tumor immunity." (PMID 35198900, 2022). "Moreover, in agreement with B16F1 tumor profiling, the frequency of FoxP3+CD4+ Treg cells was comparable in YUMM3.3-βΑ and -Ctrl tumors." (PMID 35580932, 2022). "Taken together, our data revealed that oxidative stress may reshape tumor immune environment by activating CD4+ T and CD8+ T cell, and thus affect the prognosis of PAAD patients." (PMID 36713541, 2022). "Further to this, the ratio of CD4+CD25+FOXP3+ Tregs to effector CD8+ T cells in the tumor can be an important predictor of mortality in ovarian cancer, with higher amounts of Tregs compared to the effector CD8+ T cells being correlated with poorer clinical outcomes and reduced long-term survival." (PMID 36428581, 2022). "Notably, an expansion of CD4+IL-17+RORγT+ T cells was observed in the lamina propria of Fn-treated tumour bearing mice." (PMID 35437333, 2022). "Moreover, altered tumor metabolism via CD4+ T cells results in TNF-α-dependent intensified oxidative stress and tumor cell deaths." (PMID 36860211, 2022). "Our analysis therefore suggests that the previously uncharacterized lncRNA LINC00892 could be a useful biomarker for the detection of CD4+ memory T cells in both normal and tumor tissues." (PMID 35736637, 2022). "Therefore, following a second antigen recognition, memory CD4+ T cells undergo rapid cloning and proliferation to promote tumor-specific CD8 immunity, which protects the host from tumors." (PMID 35837100, 2022). "PD-L1+TAMs and PD-1+ CD4 T cells are in contact with PD-L1+ tumor cells." (PMID 36313712, 2022). "By the analysis of TIMER database, we discovered that FAM72B expression in LUAD was negatively associated with the expression levels of B cells, CD4+ T cells, CD8+ T cells, neutrophils, macrophages, and dendritic cells but positively associated with tumor purity." (PMID 35707363, 2022).
tumor (continued). "As might be expected, in this study, we also observed that the proportion of CD4+CD25+Fox3+ cells (Tregs) in the right tumor was increased after local injection of the EPI gel, while CD3+CD8+ T lymphocytes were slightly reduced." (PMID 36605217, 2022). "Interestingly, we found that CD4+FoxP3+Helios+ Treg subset and CD4+FoxP3−Helios− T cell subset in the tumor microenvironment (TME) contributed differently to the DFS in CRC patients." (PMID 35655158, 2022). "Moreover, Ruxo increased TNF, IFN-γ, perforin, and IL-2 production by CD4+ TILs, essential effector molecules in anti-tumor immunity; similar increases of IFN-γ, perforin, and GzmB were also noticed in CD8+ TILs." (PMID 36008408, 2022). "FACS analysis showed that CD24+MDSC-DCs from tumor patients could significantly inhibit CD4+T cells from differentiating into Tregs (Fig. 7DandE)." (PMID 35707772, 2022). "Similarly, HNRNPC knockdown caused an obvious increase of tumor-infiltrating CD8 positive T cells, along with elevated CD4 positive T cells." (PMID 36536402, 2022). "Extracellular bacterial proteins taken up by tumors may stimulate CD4-positive T cells via MHC class II on tumor cells." (PMID 36361781, 2022). "In addition to preventing primary T-cell activation, MDSCs secret IL-6 to attenuate functional differentiation of the tumor-specific cluster of differentiation 4+ (CD4+) T cells into effector Th1 cells and promote tumor progression." (PMID 35954156, 2022). "In one study that highlighted this immune-regulation potential, Glycyrrhiza polysaccharide was fed to CT-26 tumor-bearing mice and significantly inhibited tumor growth, increased the immune organ index, activated CD4+ and CD8+ immune cells, and increased levels of IL-2, IL-6, and IL-7 cytokines." (PMID 36090181, 2022). "CD8+ T cells and CD4+ T helper 1 (Th1) cells are major players of anti-tumour immune responses." (PMID 35053279, 2022). "Studies have shown that the cytokines secreted by Th17 cells can not only produce tumor-promoting effects by regulating tumor angiogenesis and improving tumor immune escape but also can play an anti-tumor effect by promoting the infiltration of CD4+ and CD8+ T cells into tumor tissues." (PMID 35692779, 2022). "CD4+ TCR-Ts targeting MHC class I-restricted tumor epitopes might serve as complementary therapeutics to CD8+ T cells." (PMID 35928827, 2022). "In summary, these studies demonstrated that miR-128-3p could serve as an essential regulator of tumor immunity by modulating the enrichment of CD4+ CD25+ Foxp3+ Tregs by targeting IL16 expression in GC." (PMID 34968167, 2022). "Meanwhile, CD3+, CD4+, and TNFα levels might be valuable immune indicators of tumor response, and should be paid more clinical attention." (PMID 36158692, 2022). "Notably, anti-CTLA-4 therapy, when combined with a decrease in regulatory T cells, has been shown to enhance cytotoxic CD4+ T cell anti-tumor activity." (PMID 35831288, 2022). "Furthermore, we analyzed CD3+ T, CD4+ T and CD8+ T cells in the peripheral lymph nodes that were mainly associated with tumor growth in the lymphatic system." (PMID 35822667, 2022). "Whether CD4+ Treg redirected with BiTEs or CARs can engage in anti-tumor responses in vivo will need to be investigated." (PMID 35493508, 2022). "CBX6/7 significantly correlates with immune cell infiltrations, particularly CD4+ T cells and macrophages, indicating that CBXs may also reveal immune status, hence regulating tumor status." (PMID 35969177, 2022). "Similarly, suppressive functions of pericytes in the vicinity of tumor tissue were described to control CD4+ T cell activation and elicit antigen-specific T cell anergy." (PMID 36361868, 2022). "Notably, pIL-12 GET and combination therapy induced tumor infiltration by effector CD4+ and CD8+ T cells." (PMID 36365247, 2022). "CD4+ T cells are critical for priming of tumor-specific CD8+ T cells." (PMID 35744031, 2022).
tumor (continued). "The mechanisms by which CD4+ T cells influence anti-tumor immunity has been studied extensively." (PMID 35759090, 2022). "An antiangiogenic effect has been observed to occur through the release of IFNγ by CD4+ Th1 cells, but the exact mechanism of action may be distinct when comparing different tumor models." (PMID 36159781, 2022). "Additionally, increased levels of intratumoral Tregs expressing ICs inhibit the activation and proliferation of cytotoxic CD8+ T cells and CD4+ effector T cells within the tumor." (PMID 35455287, 2022). "Based on our results, we believe that some of the keys to the success of an immunotherapy targeting MHC-II tumors are (a) proper activation of tumor-specific CD4+ T-cells and (b) identification of potential neo-antigens against which an efficient CD4+ T cell-based response can be induced." (PMID 35655709, 2022). "Immunosuppressive cells [i.e., regulatory T cells (Tregs, Foxp3+ T)] are a part of infiltrating CD4+T-cell in the TME, which significantly inhibit the T-cell-mediated anti-tumor effect and may be associated with T-cell dysfunction." (PMID 35720388, 2022). "The exact mechanism through which neoantigen-specific CD4 T cells mediate tumor regression is unknown at this point." (PMID 36569934, 2022). "Furthermore, in addition to NK cells and CTLs, CD4+ T cells, DCs and B cells have been found to variously colonize tumors and their increased frequency in tumor tissues correlates with favorable patient prognosis." (PMID 35392082, 2022). "However, predicted immune infiltrate was significantly greater in the EPIMMUNE derived cluster group with lower tumor purity (p = 0.035), potentially due to increased CD4 memory resting T cells (p = 0.049) or resting mast cells (p = 0.002)." (PMID 35260776, 2022). "On the one hand, endogenous activin A may suppress anti-tumor immunity by inducing differentiation of Tr1, deactivating innate immune cells or inhibiting cytokine secretion from CD4+ T cells." (PMID 35774793, 2022). "However, in the time-independent study, a significant increase of tumour CD4+ T cells and increased expression levels of CD44 marker on these cells were observed in nsECT4-treated compared to untreated tumour-bearing mice." (PMID 36551739, 2022). "Based on the annotations of cells, we found the major types of tumor-infiltrating immune cells, including B cells, T cells, CD4+ T cells, CD8+ T cells, dendritic cells, NK cells, monocytes, and progenitors, to be present in ESCC, with HPSE predominantly located on monocytes." (PMID 35840985, 2022). "Moreover, smaller tumor volume and lighter tumor weight were detected in mice injected with Olfr29‐ps1‐knockdown MDSCs, and an increased number of CD4+ and CD8+ T cells was found in the tumor tissues compared with the control group." (PMID 34080276, 2022). "Moreover, LPAR2 is more important for regulating tumor purity and the infiltration of B cells and CD4 + T cells in HNSC as well as the infiltration of neutrophils and DCs in KIRC." (PMID 35241179, 2022). "The frequencies of CD4+IFN-γ+TNF-α− and CD8+IL-10+ T cells showed the most positive associations with the parameters known to be indicators of a poor prognosis such as LNs involvement, larger tumor size and higher stage of the disease." (PMID 36376825, 2022). "Moreover, we found that IgG control treatment in tumor model resulted in decreased number of CD4+ and CD8+ T-bet+TNF-α+ T cells which were induced by the anti-IL-9 antibody treatment." (PMID 35514957, 2022). "Additionally, Treg cells from AOM/DSS-treated mice have a suppressive effect on CD4+ and a more remarkable one on CD8+ T-cells, which was also associated with a tumor–promoting function in CAC." (PMID 35163788, 2022). "Tumor vaccines activate the CD4+ and CD8+ T-cell response, resulting in IFN-γ production." (PMID 36477638, 2022). "Interestingly, the tumor spheroids in 3D cultures upregulated CCR5 expression on CD4+ T cells, but the effect was counterbalanced by CAFs." (PMID 35954489, 2022).